HK2 (hexokinase 2)
Diseases named in the same sentence as HK2 in open-access papers (continued):
Sharing a sentence is not in itself a finding about the gene and the disease.
breast cancer (continued). "For example, it has been reported that miR-591 inhibited cell malignancy and glycolysis by targeting HK2 in breast cancer." (PMID 33658057, 2021). "So, circRNF20 promoted the proliferation and Warburg effect in breast cancer cells by ensuring the HIF-1α-mediated expression of HK2 in them." (PMID 33806538, 2021). "HK2 serum mRNA and HK2 specific antibodies have been proposed in aiding early diagnosis in breast cancer as their levels in patients with ductal carcinoma in situ were significantly higher than in healthy women." (PMID 34778024, 2021). "It has been revealed that TNFα/YAP/p65/HK2 signaling is able to mediate the migration of breast cancer cells." (PMID 34126594, 2021). "HK2 was highly expressed in several tumours, including breast cancer, ovarian cancer, gastric cancer, bladder cancer, lung cancer and hepatocellular carcinoma." (PMID 34664737, 2021). "The study demonstrated that miR-7641 decreased breast cancer cell glycolysis by HK2, GLUT1, LDHA which regulated by HIF-1α." (PMID 34238918, 2021). "As one of the oncogenic transcriptional factors regulating the glycolytic phenotype of breast cancer, c-myc can drive glycolytic programming by directly up-regulating the transcription of glycolysis-related genes including GLUTs, HK2, and LDHA." (PMID 35096814, 2021). "Increased therapy responses have recently been reported when HK2 was inhibited with 3-bromopyruvate in hepatocarcinoma and breast cancer, with resveratrol or sinomenine in lung cancer, with lonidamine in cholangiocarcinoma, and with luteolin in gastric cancer." (PMID 33922558, 2021). "ETV4 loss significantly inhibits the expression of HK2, LDHA as well as other glycolytic enzymes, reduces glucose uptake and lactate release in breast cancer cells." (PMID 34052833, 2021). "HK2 overexpression is also correlated with prognosis in tumors of the digestive system, including stomach, liver, pancreas, colon, and rectum, and breast cancer metastasis." (PMID 33922558, 2021). "To validate the involvement of the miR-216b-HK2-mTOR regulatory axis in breast cancer cells, we performed a rescue experiment." (PMID 34345220, 2021). "Conditional knockout mice showed that Hk2 was required for tumor initiation and maintenance in Kras-driven lung cancer and Erbb2-driven breast cancer." (PMID 33052246, 2020). "There are several studies described the role of HK2 as essential in tumor initiation and development in breast cancer; therefore, HK2 deletion as a cancer treatment have therapeutic value with no adverse physiological side effects." (PMID 32874134, 2020). "High expression of MZF1, HK2, or PGK1 was also associated with poor survival of patients with breast cancer, endometrial carcinoma, glioma, head and neck carcinoma, lung cancer, lymphoma, pancreatic cancer, or renal clear cell carcinoma." (PMID 32042322, 2020). "Kaplan–Meier analyses of overall and relapse-free survival in ER+/HER2+ breast cancer patients revealed that HK2 high-expressing tumors are characterized by worse prognosis, independently of HER2, ESR1 and proliferation status measured using MKI67 levels." (PMID 32164162, 2020). "We have already reported that breast cancers that express higher levels of HK2 are characterized by worse prognosis in a cohort of ER+ breast cancer patients that received ET." (PMID 32164162, 2020). "HGF enhanced expression of glucose transporters GLUT-1 and GLUT-4 in myocytes, increased glucose consumption and lactate production in a breast cancer model, and induced hexokinase 2 (HK2) expression in a lung cancer model." (PMID 31940827, 2020). "Application of Gen-27 to breast cancer cells led to a decrease in HK2 expression and the dissociation of HK2 from VDAC." (PMID 32843908, 2020). "Collectively, we first determined the synergistic anti‐cancer effects of PD and 2‐DG coutreatment and found that the effect was mediated by the ROS/PI3K/AKT/HIF1α/HK2 and glycolysis pathways in breast cancer." (PMID 30920152, 2019).
breast cancer (continued). "The first committed step in glucose metabolism is catalyzed by hexokinase, and previous studies showed that cancer cells express a high level of HK2 to increase glucose uptake in lung cancer and breast cancer." (PMID 31847435, 2019). "Overall, the PD and 2‐DG combination inhibits glycolytic metabolism by suppressing HIF1α/HK2 in breast cancer cells." (PMID 30920152, 2019). "Under hypoxia, glucose consumption, lactate production and HK2 protein level were enhanced in breast cancer cells, indicating that glycolysis was triggered." (PMID 31488193, 2019). "The expression of HK2 is significantly increased in brain metastatic derivatives of breast cancer cells." (PMID 31027222, 2019). "Hexokinase-II (HK2) is a key enzyme involved in glycolysis, which is required for breast cancer progression." (PMID 29985480, 2018). "Although HK2 is upregulated in breast cancer, the molecular mechanisms of HK2 involved in post-translational modifications are not clear." (PMID 29985480, 2018). "To investigate the role of HK2 T473 phosphorylation in breast cancer cell proliferation, cell migration, and tumor growth, we used stable HK2 shRNA MCF-7 cells with reconstituted expression of HA-tagged HK2 (WT, T473A, or T473D)." (PMID 29985480, 2018). "To determine the mechanisms underlying PIM2 functions in breast cancer, we performed mass spectrometry analyses of the immunoprecipitated PIM2 complex in MCF-7 cells, and found that HK2 was associated with PIM2." (PMID 29985480, 2018). "Gao and colleges found that YAP/TEAD/p65 complex binds to the promoter region of HK2 to synergistically regulate HK2 transcription and ultimately promotes glycolysis in breast cancer cells." (PMID 30176928, 2018). "Multiple studies have shown HK2 is essential for cancer growth and development, including in models of breast cancer, lung cancer, and leukemia, leading to interest in HK2 as a potential drug target for cancer therapy." (PMID 30140438, 2018). "Here, we discovered a novel interaction between PIM2 and HK2 proteins, both of which were upregulated and correlated with each other in human breast cancer tissues." (PMID 29985480, 2018). "Together, the results showed that phosphorylation of HK2 by PIM2 was important for breast cancer progression in vivo." (PMID 29985480, 2018). "To investigate if PIM2 and HK2 conferred paclitaxel resistance in breast cancer cells, we analyzed the effects of PIM2 and HK2 knockdown on the cell proliferation rates of MCF-7/TaxR cells following paclitaxel treatment." (PMID 29985480, 2018). "Taken together, our findings indicated that PIM2 was a novel regulator of HK2, and suggested a new strategy to treat breast cancer." (PMID 29985480, 2018). "Simultaneously, miR-143 positively regulates HK2 protein expression at the post-transcriptional level in breast cancer." (PMID 29156804, 2017). "Studies have uncovered the potential role of STAT3 activation in glycolysis of cancer cells via HK2 pathway in breast cancer and ovarian cancer cells." (PMID 28445971, 2017). "Further, a negative correlation was established between patient survival and HK2 expression in hepatocellular carcinoma and brain metastases of breast cancer." (PMID 29220380, 2017). "Inhibiting the expression of HK2 can inhibit the proliferation and survival of tumour cells in the breast cancer cell line MDA-MB-231." (PMID 29156804, 2017). "One example refers to the indirect action of miR-155 in a miR-143 dependent manner, resulting in the upregulation of hexokinase 2 (HK2)—an enzyme which influences the energy metabolism process demonstrated in breast cancer cells." (PMID 28703782, 2017). "Previous studies have demonstrated that HK2 is highly present in lung and breast cancers, and is required for tumor initiation and maintenance." (PMID 29285270, 2017). "A previous study also demonstrated that miR-143 and STAT3 regulated the expression of hexokinase 2 in breast cancer cells." (PMID 27767041, 2016).
breast cancer (continued). "Recently, one study indicates that activation of Beta2AR can promote HK2 expression, and inhibition of Beta2AR can decrease HK2 expressions in breast cancer cell lines." (PMID 27255554, 2016). "HK2 participates in tumor initiation and maintenance, and HK2 depletion inhibits the neoplastic phenotype of human lung and breast cancer cells in vitro and in vivo." (PMID 27255554, 2016). "Previous study indicates that activation of Beta2AR can promote HK2 expression, and inhibition of Beta2AR can decrease HK2 expressions in breast cancer cell lines." (PMID 27255554, 2016). "Evidently, metformin directly inhibits the enzymatic function of HK1 and HK2 in breast cancer cells and markedly reduces tumor glucose consumption and growth." (PMID 26576639, 2015). "Additionally, HK2, a key enzyme in the glycolytic pathway, plays a crucial role in AI-resistant breast cancer." (PMID 40303296, 2025). "Additionally, compared with normal tissues, breast cancer samples exhibited significantly increased expression of HK2." (PMID 39991762, 2025). "Upregulation of HK2 can induce drug resistance in breast cancer cells." (PMID 40612109, 2025). "In summary, evidence suggests that GLUT1, HK2, LDHA, MCT1, PKM2 and PFK1 could become potential biomarkers, either diagnostic or prognostic, in breast cancer, depending on the molecular subtypes and treatment involved." (PMID 41154605, 2025). "HK2 is usually induced to catalyze glucose metabolism in cancer cells and is highly expressed in various tumors, including prostate cancer, liver cancer, gastric cancer (GC), glioblastoma, and breast cancer." (PMID 38581001, 2024). "Besides, H2AX promotes metastatic progression in breast cancer cells by preserving glycolysis via hexokinase-2." (PMID 38566813, 2024). "In addition to HK2, the hypoxia-inducible form of 6-phosphofructo-2-kinase (PFKFB3) is another glycolytic enzyme implicated in promoting aerobic glycolysis in breast cancer." (PMID 39408832, 2024). "Moreover, another work demonstrated that HK2 also has an important role in the stemness of cancer cells, including in breast cancer." (PMID 39201646, 2024). "To determine whether aerobic glycolysis regulates the NF-κB in breast cancer cells, we overexpressed Flag-HK2 in MCF-7 cells." (PMID 37377974, 2023). "Let-7b-5p negatively correlates with HK2 in patients with breast cancer." (PMID 37019900, 2023). "Recent reports showed that blocking the PI3K/AKT signaling pathway could suppress HK2 expression in both hepatocellular carcinoma and breast cancer cells." (PMID 37259304, 2023). "Collectively, these results indicate that CMA could promote breast cancer angiogenesis via regulation of HK2-dependent aerobic glycolysis, which may serve as an attractive target for breast cancer therapies." (PMID 36913368, 2023). "Consequently, miR-591 silencing and overexpression of hexokinase 2 (HK2) mimicked the circ0069094 inhibition-mediated effects on cell growth, apoptosis, and glycolysis in breast cancer cells." (PMID 37243750, 2023). "In addition, the clinical significance of HK2-upregulated PD-L1 expression is evidenced by the positive correlation of HK2 with IκBα T291 phosphorylation and PD-L1 expression in human breast cancer samples." (PMID 37377974, 2023). "Additionally, it has been found that HK2 activity is higher when the lesions metastasize in breast cancer." (PMID 37580808, 2023). "MiR-143 directly inhibits HK2 and negatively regulates glycolysis in breast cancer cells." (PMID 37204526, 2023). "circRAD18 functions as a miR-613 sponge to upregulates HK2 and further exacerbate breast cancer." (PMID 37204526, 2023). "Moreover, tumor metastasis suppressor gene-1 (MTSS1) regulates aerobic glycolysis in breast cancer by affecting HK2 kinase activity, and inhibits aerobic glycolysis in breast cancer by competitively binding to mitochondria-targeted HK2." (PMID 36672448, 2023).
breast cancer (continued). "A better understanding of the circRNF20/miR-487a/HIF-1/HK2 axis in breast cancer progression and the Warburg effect may provide new insights into breast cancer." (PMID 37243750, 2023). "In fact, it has been previously observed that EGF signaling activates the first step in glycolysis with hexokinase 2 (HK2) but impedes the last step with pyruvate kinase muscle isozyme M2 (PKM2) in triple breast cancer cells, and that PKM2 expression is aberrantly high in osteosarcoma tissues." (PMID 36980255, 2023). "HK2 is overexpressed in ErbB2-driven breast cancer for tumor initiation and maintenance." (PMID 37190124, 2023). "Finally, we found that lactate regulation in breast cancer cells is hexokinase 2 (HK2) dependent, and knockdown of HK2 can significantly reduce the ability of CMA-mediated tube formation capacity of HUVECs." (PMID 36913368, 2023). "Our findings indicate that the let-7b-5p/HK2 axis plays a key role in aerobic glycolysis as well as breast tumor proliferation and metastasis, and targeting this axis is a potential therapeutic strategy for breast cancer." (PMID 37019900, 2023). "Bioinformatic analysis showed that HK2 expression is associated with upregulated CD274 mRNA expression, reduced infiltration of CD4+ and CD8+ T cells in breast cancer specimens, and decreased survival time of breast cancer patients." (PMID 37377974, 2023). "To determine whether HK2 expression is correlated with PD-L1 expression in human breast cancer specimens, we analyzed 1100 breast cancer cases in The Cancer Genome Atlas (TCGA) database." (PMID 37377974, 2023). "In addition, circHIPK3 also regulates the drug resistance of breast cancer cells to paclitaxel through the circHIPK3/miR-1286/Hexokinase 2 (HK2) axis." (PMID 35205613, 2022). "Some studies indicate that breast cancer cells exhibit a high level of HK2 expression." (PMID 36059650, 2022). "Additionally, it is clear that HIF-1α can bind with location 1 of the HK2 promoter where it is an upstream promoter site of HK2 and facilitates the transcription of HK2, which accelerates glycolysis and promotes breast cancer." (PMID 36230935, 2022). "The malfunction of HK2 in breast cancer cells tends to be modulated using ncRNAs such as miRNA." (PMID 36230935, 2022). "HK2 is mainly expressed in insulin-sensitive tissues and predominant in malignant or rapidly proliferating tumors (such as cervical cancer, breast cancer, lung cancer, prostate cancer, hepatocyte cell cancer), deleting HK2 inhibits tumor progression with no sign of adverse physiological effects." (PMID 35953860, 2022). "Similarly, the oncogenic role of HK2 has been studied in various cancer conditions, including lung, pancreatic, and colorectal cancers; brain metastasis of breast cancer; and renal carcinoma." (PMID 35328104, 2022). "Increased glycolytic activity is also explained by the greater activity of some of the enzymes in the pathway, such as hexokinase 2, which is overexpressed in breast cancer and whose inhibition in transgenic mice that develop breast cancer after overexpression of ErbB2/Neu delays tumor development." (PMID 35053485, 2022). "Finally, our results showing that systemic HK2 deletion after tumor onset, which emulates drug therapy, inhibited breast cancer metastasis provided a proof of concept for targeting HK2 to inhibit breast cancer metastasis." (PMID 35173161, 2022). "We first wanted to determine if systemic deletion of HK2 after primary breast tumor onset that emulates drug therapy could inhibit breast cancer metastasis." (PMID 35173161, 2022). "So, the role of HK2 in breast cancer deserves to be further investigated." (PMID 36335239, 2022). "HK2 has been identified as a potential molecular marker of prognosis in gastric adenocarcinoma, glioblastoma multiforme, laryngeal squamous cell carcinoma, and breast cancer." (PMID 35265223, 2022).
breast cancer (continued). "Additionally, a combination treatment involving polydatin and 2-deoxy-d-glucose in breast cancer induced apoptosis by targeting ROS/PI3K/AKT/HIF-1α/HK2." (PMID 34577602, 2021). "For instance, knocking-out HK2 expression prevents or strongly inhibits tumor formation in genetic mouse models of lung and breast cancer and of PTEN-negative prostate cancer, while liver-specific ablation of HK2 decreases tumor incidence in a mouse model of hepatocarcinogenesis." (PMID 33946854, 2021). "It was demonstrated that knocking-down HIF-2α in MDA-MB-231 breast cancer cells significantly decreased the expression of glycolysis-related gene products, such as HK2, LDHA, SLC2A1 and PDK1, consisting with the suppression of mRNA levels of glycolysis- and hypoxia-related genes." (PMID 35096814, 2021). "(Over)expression of HK2 is also linked to tumor progression and/or metastasis in a variety of diverse neoplastic models including HCC, colorectal carcinoma, lung cancer, breast cancer, prostate cancer, diffuse large B-cell lymphoma and glioblastoma." (PMID 33946854, 2021). "However, the expression of HK2 in breast cancer, colorectal cancer and leukemia was lower than that in normal tissues." (PMID 34708035, 2021). "Increased PPP flux by G6PD and HK2 enhancement induces tamoxifen resistance in breast cancer." (PMID 34552932, 2021). "Moreover, tamoxifen-resistant breast cancer cells MCF-7 showed upregulation of HK2 and mTOR that was accompanied by an enhanced glycolysis process." (PMID 32874134, 2020). "In this regard, we previously made similar observations for mTORC2-targeted loss of hexokinase 2 (HK2) in HER2-mut breast cancer cells (not shown)." (PMID 32923403, 2020). "For instance, HK2 is the first rate-limiting enzyme of glycolysis, and its activity has been predicted to be regulated by multiple miRNAs including the confirmed negative regulation by miR-143 in breast cancer cell lines." (PMID 33425736, 2020). "At molecular level, previous study has shown that HK2 is essential for tumor initiation and survival in Kras-driven mouse lung cancer and ErbB2-driven mouse breast cancer, indicating that HK2 could be important to regulate cancer stemness." (PMID 32195170, 2020). "In addition, we also found that targeting HK2 with siRNA can block breast cancer cell survival and this result was consistent with PD and 2‐DG co‐treatment (Figures 5C5, 6, 7)." (PMID 30920152, 2019). "HK2 deletion in breast cancer cells thus improved the anti‐cancer activity of 2‐DG." (PMID 30920152, 2019). "HK2 is highly expressed in many cancers, including breast cancer, ovarian cancer, and colon cancer." (PMID 31569385, 2019). "Notably, HK2 is required for tumor initiation and maintenance in mouse models of K-Ras-driven lung and ErbB2-driven breast cancers." (PMID 31212816, 2019). "In addition, HK2 has been shown to promote glycolysis and tumor growth in vivo in glioblastoma, medulloblastoma and breast cancer." (PMID 31212816, 2019). "As a result, phosphorylated HK2 Thr473 promoted breast cancer cell growth in vitro and in vivo." (PMID 29985480, 2018). "Importantly, phosphorylation of HK2 on Thr473 promoted glycolysis and was required for breast cancer cell growth in vitro and in vivo." (PMID 29985480, 2018). "Furthermore, stably rHK2 (T473A) MCF-7 cells also had decreased resistance to paclitaxel compared with rHK2 (WT or T473D) MCF-7 cells, which suggested phosphorylation of HK2 at T473 played a crucial role in the resistance of breast cancer cells." (PMID 29985480, 2018). "Our data further suggested that the PIM2-mediated HK2 phosphorylation may provide a potential therapeutic target for the treatment of breast cancer." (PMID 29985480, 2018). "The HK2 T473 phosphorylation might be involved in regulating aerobic glycolysis of breast cancer cells." (PMID 29985480, 2018). "YAP mediates TNFα-induced expression of HK2 and glycolysis in breast cancer cells." (PMID 28945218, 2017).